CCR2 (C-C motif chemokine receptor 2)
Diseases named in the same sentence as CCR2 in open-access papers (continued):
Sharing a sentence is not in itself a finding about the gene and the disease.
tumor (continued). "Taken together, the CCL2/CCR2 signaling axis is involved in a wide range of tumor cell activities, and regulation of CCL2 and/or CCR2 expression influences tumor progression." (PMID 35702353, 2022). "CCL2 is a key chemoattractant of CCR2+ monocytes that can differentiate into tumor-supportive MDSCs and TAMs." (PMID 36568151, 2022). "The signaling of CCL2/CCR2 is well known to promote macrophage infiltration and activation, consequently contributing to tumor growth and progression." (PMID 35094142, 2022). "It has been shown that mast cells can induce further tumor cell invasion by regulating EMT via the ERβ/CCL2/CCR2 signaling axis (Erβ, estrogen receptor β)." (PMID 36611857, 2022). "Many other preclinical studies on different tumor types showed that either depletion of CCR2 or disruption of the CCL2-CCR2 interaction has an impact on the inhibition of TAM recruitment and tumor regression or inhibition of metastasis." (PMID 35592338, 2022). "As the primary source of CCL2, FAP+ CAFs undergo crosstalk with circulating MDSCs expressing the CCL2 receptor (CCR2), thereby forming a CCL2–CCR2 axis that plays a role in mediating tumor promotion." (PMID 36263225, 2022). "Results of qRT-PCR partially demonstrated the bioinformatics results that the mRNA levels of CXCL10, CXCL9, CCL5, and CCR2 were remarkably elevated in tumor tissues collected from PTC patients coexistent with HT than those without HT." (PMID 36266640, 2022). "Accordingly, CCR2 antagonist decreased tumor growth and dissemination of DLBCL cells, and increased survival in xenograft models." (PMID 36578079, 2022). "The author also constructed a mouse model and demonstrated that a combination of CCR2 antagonists with cabazitaxel was more effective at inhibiting tumor growth than cabazitaxel and CCR2 antagonists alone." (PMID 36077785, 2022). "Chemokines have long been implicated in macrophage accumulation within tumours and their inhibitors, such as anti-CCL2 or CCR2 blockade, have been successfully tested in experimental tumours." (PMID 36439180, 2022). "Blocking monocyte migration with a CCR2 antagonist reduced the infiltration of CD169+ macrophages into the tumor." (PMID 36266311, 2022). "CCR2 expression by tumor cells can respond in a paracrine fashion to CCL2 produced by various non-tumor cells, tumor cells can also produce CCL2 which acts on CCR2 on tumor cells via an autocrine fashion." (PMID 34804061, 2021). "Enhanced CCL2 release by irradiated tumor cells contributes to the recruitment of inflammatory monocytes and CCR2+ Tregs." (PMID 34386431, 2021). "CCL-2 and CXCL-12 can aid in angiogenesis and impede endothelial cells' apoptosis through straight receptor (CXCR-4 and CCR-2) binding on tumour vessels or obliquely propping up drafting in leukocytes." (PMID 34336101, 2021). "CCL2 can bind to its receptor CCR2 and play an important role in tumor development and metastasis by regulating tumor cell growth and survival, angiogenesis, tumor invasion, and metastasis." (PMID 33414423, 2021). "It was also reported that tumor-specific vaccination induced migration of CCR2+ Tregs into the tumor region." (PMID 34386431, 2021). "CCL2 neutralizing antibodies or CCR2 antagonists have been developed to potentiate anti‐tumour effects and have produced encouraging results in some preclinical studies." (PMID 34464477, 2021). "We surmise above that CCR2 has enhancing effects on two main types of immunosuppressive immune cells to promote tumor progression and metastasis." (PMID 34804061, 2021). "The results certified that the transcriptome level of CCR2 was significantly reduced in tumor tissues." (PMID 34251980, 2021). "Of note, CCR2 expression by tumor cells is also subject to regulation by its own ligands, as CCL2 has been shown to downregulate CCR2 in tumor cells." (PMID 34804061, 2021).
tumor (continued). "Using mouse glioma models which enable the differentiation of genetically labelled MDM (Ccr2 RFP) and MG (Cx3cr1 GFP), they showed that microglia associated tumor cells increase tumor cell phagocytosis in response to CD47/SIRPA axis inhibition." (PMID 34168976, 2021). "In mouse models, inactivation of CCL2-CCR2 signaling achieved by gene knockout or inhibition of CCR2 by small molecule inhibitors reduced tumor growth and metastatic spread." (PMID 34771482, 2021). "C-C chemokine receptor type 2 (CCR2) is also expressed by macrophages in response to the production of chemoattractant protein-1 (CCL2) expressed by tumor cells." (PMID 33408768, 2021). "It has been shown that tumor-derived CCL2 supports tumor growth, depending on CCR2 expression by host cells in mouse models of transferred liver cancer cells." (PMID 34804061, 2021). "We found that mice inoculated with 1 × 104 CCL16-overexpressing MDA-MB-231 cells demonstrated a dramatically increased incidence of tumor initiation versus mice inoculated with control cells and that CCR2 knockdown prevented this increased tumor incidence." (PMID 33500726, 2021). "It has been reported across multiple murine tumor- and metastasis models that CCR2 antagonism in combination with anti-PD-1 therapy lead to sensitization and enhanced tumor response over anti-PD-1 monotherapy." (PMID 34094963, 2021). "Paradoxically, CCR2-expressing monocytes/macrophages, particularly in tumor microenvironments, can be strongly immunosuppressive." (PMID 34804061, 2021). "Nevertheless, CCR2 inhibition appears to affect the regulatory immune cell compartment preferentially and displays promising anti-tumor effects." (PMID 34065010, 2021). "The results showed that knockdown of KLRG1 also reduced the expression of BTK and CCR2 in A549 tumor cells." (PMID 34187403, 2021). "Ccne1−/− tumours revealed diminished levels of Ccr2 and Ccr5, which further indicates the decrease in infiltrating myeloid subpopulations in absence of CCNE1." (PMID 34830835, 2021). "Such a CCR2-assoicated immunosuppressive network is further entangled with paracrine and autocrine CCR2 signaling of tumor cells." (PMID 34804061, 2021). "Although L-MSCs behave not differently from BM-MSCs in their effects on adaptive immune cells, they are more effective in recruiting monocytes/macrophages via CCR2, which positions L-MSCs a much stronger tumor-promoting population than BM-MSCs." (PMID 34513701, 2021). "Strategies to target CCL2/CCR2 axis as cancer therapy in the view of three types of CCR2-expessing cells in tumor microenvironment are discussed." (PMID 34804061, 2021). "GMME1 specifically blocked CCR2‐associated STAT3 phosphorylation and induced tumour cell apoptosis, thereby inhibiting tumour proliferation." (PMID 34464477, 2021). "Together with the paracrine and autocrine CCR2 signaling of tumor cells, CCR2 has a significant role in tumor growth and metastasis." (PMID 34804061, 2021). "In this section, we mainly consider tumor metastasis/invasion from the angle of direct CCR2 signaling of tumor cells." (PMID 34804061, 2021). "In many preclinical models, including melanoma, breast, and bladder cancers, CCR2 antagonism coupled with anti-PD-1 therapy enhanced the anti-tumor response of mice compared to anti-PD-1 monotherapy." (PMID 34065010, 2021). "Blockade of CCL2/CCR2 signaling pathway suppressed monocyte recruitment and the polarization of infiltrated macrophages towards the M2 phenotype, suppressing tumor growth in a T cell-dependent manner, in a mouse liver cancer model." (PMID 33531974, 2021). "CCL2 can be produced by multiple cell types in the tumor environment, while CCR2 can also be expressed by multiple cell types including tumor cells." (PMID 34804061, 2021). "RS 504393 is a selective CCR2 antagonist that delays tumour progression by inhibiting the infiltration of immunosuppressive cells into tumour sites." (PMID 34464477, 2021).
tumor (continued). "CCL2 via its receptor CCR2 controls the migration of regulatory T cells (Treg) and myeloid suppressor cells, as well as their ability to promote tumor growth." (PMID 34504786, 2021). "In the murine AOM/DSS model of CAC, the contribution of macrophages to tumorigenesis was corroborated by specifically blocking the CCR2-dependent recruitment of macrophages, which was sufficient to prevent tumor development." (PMID 34025672, 2021). "Knockdown or antibody neutralization of CCL2 in breast xenograft models inhibits infiltration of CCR2+ macrophages and reduces tumor growth and metastasis." (PMID 33888841, 2021). "CCL2 secreted by tumor cells can attract Th1 cells, Th17 cells and macrophages, which express high levels of CCR2, to the tumor site." (PMID 34683963, 2021). "In a recent study, VPA was shown to downregulate CCR2 expression in M-MDSCs, and the tumor invasion ability of these cells was also reduced." (PMID 34149732, 2021). "The CCL2/CCR2 signaling axis plays a central role in regulating the infiltration of circulating monocytes into the tumor microenvironment, making it a promising TAM-targeting therapy." (PMID 34201127, 2021). "Next, we uncovered the correlation of the CCR2 expression with clinical factors, such as age, grade and stage of tumor, histological type and cancer status after operation." (PMID 34251980, 2021). "Among them, P2RY13 showed a more statistically statistical difference than CCR2 in normal and tumor tissue." (PMID 34494914, 2021). "As with CXCR2, the CCR2/CCL2 axis is also involved in recruiting myeloid cells to the tumor microenvironment." (PMID 34203869, 2021). "CCL2 (MCP1), which interacts with CCR2, is an alternative mechanism that influences macrophage-related myeloid recruitment to tumors and subsequent tumor progression." (PMID 33953710, 2021). "The CCR2 antagonist blunted the reduction in tumor growth (mean volume in mm3 at day 10: vehicle = 110.4; RvD1 = 68.23, CCR2 antagonist = 88.51; CCR2 antagonist+RvD1 = 155.8) as well as the improvement in survival observed in RvD1-treated mice." (PMID 33845864, 2021). "In vivo studies in tumor-bearing CCR2 knock-out mice and CSF-1 depleted tumor graft models have shown reduced TAM density, inhibition of protumor cytokine expression, and prolonged survival in these mice." (PMID 34439281, 2021). "Using CCL2 binding as a way detecting CCR2-expressing cells, tumor Tregs contained >50% CCR2+ while proportions of CCR2+ Tregs in circulation and draining LNs were much lower." (PMID 34804061, 2021). "CCR2 mediated recruitment of blood monocytes or M-MDSCs to tumor tissues results in a high abundance of TAMs that is often associated with poor clinical outcomes in patients." (PMID 34804061, 2021). "And a lower expression levels of KLRG1, BTK, CCR2, SCML4 were all associated with advanced neoplasm disease stage." (PMID 34187403, 2021). "A series of elegant mouse studies from Jeffrey Pollard’s group has greatly contributed to our understanding of the biology of MAMs, in particular, how CCL2-mediated recruitment of CCR2+ tumor-promoting inflammatory monocytes facilitates metastasis." (PMID 33924237, 2021). "CCL2 acts on CCR2 to advance the tumor, whereas, in CCR4, it acts to recruit cytotoxic T lymphocytes and exert an anticancer effect." (PMID 34445235, 2021). "CCL7 secreted by Mo-MDSCs binds to CCR2 of dormant cells and promotes the transition from tumor dormancy to metastatic outgrowth through the JAK-STAT3 signaling pathway." (PMID 33986252, 2021). "CCR2 inhibitors enhanced the therapeutic effect of anti-PD-1 antibodies in several mouse tumor models." (PMID 34445235, 2021). "We surveyed the literature for CCR2 expression by various human tumor cell lines as well as patient samples and found that all types of solid and blood cancers expressed either CCR2." (PMID 34804061, 2021).
tumor (continued). "CCR2 is overexpressed in immunosuppressive cells and tumour cells, but its relatively low expression in most normal tissues make this receptor a promising target in cancer." (PMID 34464477, 2021). "Combination therapy of CCR2 antagonist and anti‐PD‐1 also improved anti‐tumour effects compared with monotherapy." (PMID 34464477, 2021). "Our data show that Poly6 versus PBS treatment led to enhanced transcription levels of IL-12 and CCR2 in tumor tissues." (PMID 33499256, 2021). "More importantly, TA-MSCs can recruit macrophages and myeloid-derived suppressor cells (MDSCs) into the tumor microenvironment through CC-chemokine receptor 2 (CCR2) ligands, including CC-chemokine ligand 2 (CCL2), CCL7, and CCL12." (PMID 33889575, 2021). "Next, we checked the transcription level of IL-12 and CC chemokine receptor type 2 (CCR2), markers of Tip-DC development in cancer tumor tissue via RT-qPCR." (PMID 33499256, 2021). "Immunostaining showed that CRC cells derived CCL2 govern the macrophage infiltration and polarization in the tumor by interacting with CCR2." (PMID 34580284, 2021). "Ccr2-expressing macrophages, which are reduced in G-Smo tumors, have been shown to suppress tumor growth." (PMID 34021242, 2021). "Targeting the CCL2/CCR2 pathway, responsible for the recruitment of these immunosuppressive myeloid cells, enhanced anti-tumor immunity in the residual tumor, and thereby overcame the resistance to anti-PD-1 therapy." (PMID 33936033, 2021). "Abundant evidence shows that TAMs are derived from Ly6C+CCR2+ monocytes in various experimental tumor models." (PMID 34804061, 2021). "HDAC5 inhibits suppressor of cytokine signaling 3 (SOCS3), which leads to an increase of C-C motif chemokine ligand 2 (CCL2), recruits CCR2+ macrophages, promotes macrophages to reaggregate into tumor microenvironments, and promotes tumor recurrence." (PMID 34880761, 2021). "In different cancers, crosstalk between TAMs and tumour cells play various roles in their growth through the CCL-2/CCR-2 axis." (PMID 34336101, 2021). "In another study, CCR2-dependent recruitment of monocytes/macrophages by tumor resident mesenchymal stromal cells was reported to facilitate tumor growth." (PMID 34336660, 2021). "For example, by blocking the most common CCL-2 and CCR-2 signaling pathways, macrophages recruitment and infiltration can be decreased, and tumor development can be delayed." (PMID 34922542, 2021). "CCL2-mediated CCR2+ monocyte recruitment in the tumor was shown to significantly enhance the killing capacity of neutrophils." (PMID 34386431, 2021). "The CCR2 inhibitor, PF‐04136309 can decrease tumour‐infiltrating inflammatory monocytes and macrophages, promoting anti‐tumour immunity in mice." (PMID 34464477, 2021). "CXCR3 and CCR2 signaling leads to the recruitment of tumor-promoting immune cells, e.g., of TAMs, T cells and myeloid-derived suppressor cells (MDSC)." (PMID 34203660, 2021). "Entinostat also inhibits the transport of M-MDSCs from bone marrow to the tumor environment by downregulating CCR2." (PMID 34149732, 2021). "Tumor-induced splenic accumulation of myeloid-biased HSPCs is related to the recruitment of circulating HSPCs via the CCL2/CCR2 axis and the subsequent local education by splenic stromal cells." (PMID 33919979, 2021). "Accordingly, cells which were grown in serum-free medium and treated with a CCL2 neutralizing antibody or a CCR2 antagonist (RS504393) had significantly decreased proliferation of tumor cells compared with untreated control cells." (PMID 34804061, 2021). "Combining CCR2 blockade (CCX872) with anti-PD-1 treatment significantly enhanced survival of tumor-bearing mice and reduced MDSCs within the tumor while the fraction of functional T cells was increased." (PMID 34203660, 2021). "Inhibition of CXCR2 and CCR2 in this model reversed infiltration of MDCSs and tumor progression and increased T-cell influx." (PMID 34203869, 2021).
tumor (continued). "To this end, we compared the GBM take rate in mice depleted of Treg cells (FoxP3DTR mice, treated with DT prior to tumor inoculation) vs. Ccr2–/– mice that are unable to recruit monocytic TAM precursors to tumor sites." (PMID 33976133, 2021). "Clusters 5 and 6 are identified as Ly6Chigh CCR2+ circulating monocytes clusters, which are recruited to the tumor and become immunosuppressive TAMs." (PMID 33974041, 2021). "While CCR2/CCR5 can regulate the density of TAMs in the TME, another signaling protein present on MDSCs, CXCR2, is known to control chemotaxis of tumor-associated neutrophils." (PMID 34771675, 2021). "Olig2-expressing tumor stem cells, Ccr2+ macrophages, and Igf1+ microglial have all been shown to affect tumor progression and prognosis." (PMID 34021242, 2021). "An objective tumor response was seen in 49% of patients receiving FOLFIRINOX plus the CCR2 antagonist PF-04136309, with local tumor control achieved in 97% of patients (NCT01413022)." (PMID 34201127, 2021). "CCL2 was a common chemokine that recruits monocytes, memory T cells, and dendritic cells during tumor progression through the CCL/CCR2 and CCL2/CCR4 signaling." (PMID 34580284, 2021). "The chemokine CCL2 and its receptor CCR2 act a pivotal part in tumor invasion and metastasis by recruiting TAMs." (PMID 33391402, 2021). "Breast cancer treated with doxorubicin showed promotion of CCL2 production by stromal cells, leading to recruitment of CCR2+ monocytes and contributing to tumor relapse." (PMID 34209703, 2021). "In brief, CCL2 promotes tumour angiogenesis by recruiting CCR2+ vascular endothelial cells and inflammatory cells and by stimulating the expression of angiogenic factors." (PMID 34464477, 2021). "More recently, Fein and colleagues found that CCR2 secreted by tumour cells orchestrated immune evasion by depressing CD103+ DC maturation and suppressing CTL activity." (PMID 34464477, 2021). "Recruitment of classical Ly6C+ blood monocytes to tumor-challenged lungs can be inhibited in a CCR2-mediated manner, reducing MAMs and alleviating metastatic burden." (PMID 33924237, 2021). "In the context of cancer, we highlight here the complex and sometimes underappreciated roles of the CCL2/CCR2 axis in regulating abundance and functions of monocytes/MØs, T cells (particularly Tregs) and tumor cells." (PMID 34804061, 2021). "Although the CCL2–CCR2 axis is primarily considered to be a chemokine pathway involved in myeloid cell-participated immune regulation, CCR2-expressing tumor cells can also directly interact with CCL2 for itself activation." (PMID 34386431, 2021). "Interestingly, CCL2 expression is dramatically increased in BCSCs based on TCGA data set and we propose a hypothesis that secretion of CCL2 from BCSCs is enhanced by LDHA, which could recruit more CCR2-positive tumor associated macrophages (TAMs) to further maintained the stemness of BCSCs." (PMID 34178639, 2021). "Antagonists of colony-stimulating factor 1 receptor (CSF1R) or of the chemokine receptor CCR2 substantially decreased the tumor-initiating properties of CSCs in pancreatic mouse tumor models." (PMID 34583655, 2021). "The direct action of CCR2 on tumor cells can also lead to survival and proliferation of tumor cells." (PMID 34804061, 2021). "Demonstrating the importance of PDAC TAMs on T cell function, antagonism of CCR2 prevents CCR2+ MonoMacs from infiltrating the PDAC TME and also causes an increase both CD4+ and CD8+ tumor infiltrating lymphocytes." (PMID 35008355, 2021). "CCL3 secretion by TAMs was found to be induced by CCL2/CCR2 and IL-33, with these TAMs reported to mediate metastatic spread in different tumor models." (PMID 34988021, 2021). "A recent study revealed that CCR2 antagonism sensitized tumors to anti-PD-1 ICB therapy in a number of murine tumor and metastasis models." (PMID 33924237, 2021).